IL13 (interleukin 13)
Diseases named in the same sentence as IL13 in open-access papers (continued):
Sharing a sentence is not in itself a finding about the gene and the disease.
tumor (continued). "In mice, ILC2s are expanded and activated through the interaction of CRTH2 and NKp30 with tumor derived PGD2 and B7H6, respectively, leading to an increased production of IL-13." (PMID 31024531, 2019). "CD4+ helper T lymphocytes react to CAF secretion of CCL2, CCL5, and CCL17 along with polarizing cytokines IL-1, IL-6, IL-13, and IL-26 by switching from an anti-tumor TH1 response to a pro-tumor TH2 and TH17 response." (PMID 31058816, 2019). "Pro-tumor: ILC2 elevate tumor-derived PGD2 and B7H6 to active MDSCs via IL-13 thus inducing immunosuppressive effects." (PMID 32117199, 2019). "Hypoxia, colony stimulating factor 1 (CSF-1), TGF- β, IL-4 and IL-13 are able to enhance the switch of TAM from M1 to M2 phenotype, thus changing the M1/M2 ratio while tumor progression." (PMID 30680411, 2019). "In addition, IL4 and IL13 could act as signaling molecules in the tumor microenvironment." (PMID 31540495, 2019). "Type II NKT cells were reported to produce IL-13 through the IL-4R–STAT6 pathway, which was necessary for downregulation of tumor immunosurveillance in a 15-12RM fibrosarcoma mouse model." (PMID 29535734, 2018). "By contrast, TH2-/Treg-like NKT cells produce large amounts of IL-13 and IL-10, respectively, that suppress the TME (i.e., via fibroblasts and MDSC), thereby indirectly stimulating tumor progression." (PMID 29535734, 2018). "In the IL13 locus, the CD4+ T cells demonstrated an increased methylation in muscle invasive pT2 tumours compared to the cells from patients with pT0 stage." (PMID 30075815, 2018). "IL-13 can signal through IL-13R via JAK/STAT and AP-1 pathways in certain cell lines including some tumor cell lines." (PMID 30572904, 2018). "TNF, IL6 and ANGPT2 were expressed equally by both DLD1 and SKBR7 xenografts, whereas higher levels of IL1B, IL4, IL13 and VEGFA were found in DLD1 tumours." (PMID 29367702, 2018). "Tumor-produced TSLP has been shown to up-regulate OX40L expression on DCs, thus inducing the generation of Th2 cells that produce IL-4 and IL-13 that have been shown to promote tumor growth in breast and pancreatic cancer." (PMID 30619378, 2018). "But, the level of IL-10, a Th2 cytokine, was significantly higher in the tumor microenvironment of wild type mice that developed invasive SCC, and only relatively low concentrations of IL-4 and IL-13 were detected." (PMID 30112116, 2018). "Tumor samples obtained from ST2KO mice presented lower levels of IFN-γ, TNF-α, IL-10, and IL-17, while the production of IL-12, IL-4, IL-13 and TGF-β was similar between tumor skin samples obtained from wild type and ST2KO mice." (PMID 30112116, 2018). "Following the development of an intraepithelial lesion, this macrophage phenotype is shifted towards an immunosuppressive subset by tumour-derived cytokines as IL4, IL10 and IL13." (PMID 30577495, 2018). "Taken together, our in vivo observations show that disruption of the novel tumour immunosuppressive axis by specifically blocking PGD2, IL-13 and NKp30 at least partially restores immunity resulting in increased survival in humanized leukaemic mice." (PMID 28928446, 2017). "In a preclinical tumor model, ADT also enhances the expression of macrophage-recruiting chemokine CSF1 and M2-promoting cytokines, such as IL13 and IL10 in PCa cells, resulting in more macrophage infiltration and expression of MMP9 and VEGF46." (PMID 29142311, 2017). "The alternatively activated M2 macrophages are stimulated by IL4 and IL13, secrete IL10, transforming growth factor-β (TGF-β), and chemokines, and are involved in tissue remodelling and tumour progression." (PMID 29065107, 2017). "We show that in vivo interference with PGD2, NKp30 and IL-13 functions in murine and humanized APL models is sufficient to significantly reverse immunosuppression and increase survival of humanized tumour-bearing mice." (PMID 28928446, 2017).
tumor (continued). "TAMS, upon arrival, can then lead to even more release of promoting cytokines: TGF-beta, MMPs, VEGF, CM/M-CSF, CCL 17, IL-13 and CCL2 which secure pro-angiogenic tumor processes." (PMID 28441391, 2017). "We cover fundamental molecular players in the tumor microenvironment including extra- (CCL2, CSF-1, CXCL12, IL-4, IL-13, semaphorins, WNT5A, and WNT7B) and intracellular signals." (PMID 28197019, 2017). "The breadth of responses includes anti-tumor effector (Granzyme B, IFN-γ, MIP-1α, TNF-α), stimulatory (GM-CSF, IL-2, IL-8), regulatory (IL-4, IL-13, IL-22), and inflammatory (IL-6, IL-17A) functions." (PMID 29157295, 2017). "Disruption of this tumour immunosuppressive axis by specifically blocking PGD2, IL-13 and NKp30 partially normalizes ILC2 and M-MDSC levels and results in increased survival in leukaemic mice." (PMID 28928446, 2017). "The result demonstrated that tumor stroma densities of CD68 and IL-13 were independent prognostic factors for patients’ overall survival (p < 0.01)." (PMID 26771842, 2016). "IL-13, MCP-1 and MIF have been shown to induce infiltration of immune cells and promote tumour progression, −invasion and metastasis in various cancers." (PMID 27206490, 2016). "Distribution densities of CD1A, IL-13 and CD68 in tumor stroma of 66 ESCC patients were further calculated with InFormTM 2.0.1 software." (PMID 26771842, 2016). "The findings have shown that protein which includes the likes of Eotaxin, Fas ligand, IGF-II, IL-1β, TNF-α, IL-13, Leptin, and TIMP-1 were decreased when compared to the untreated tumor." (PMID 27558166, 2016). "Both PGN and IR decreased IL13 production in the tumor, with the lowest level detected in the PGN + IR-treated tumor." (PMID 27708223, 2016). "Those which have been found to suppress tumor growth include IL-2, IL-12, IL-13 and IFN (gamma, beta and alpha) while IL-4, IL-6, IL-8 and IL-10 predominantly contribute to tumor growth." (PMID 24997057, 2014). "This review surveys the tumor-promoting and tumoricidal activities of several prominent cytokines: IFN-γ, TNF-α, TGF-β, IL-17, IL-23, IL-4, and IL-13, produced by three major subsets of T helper cells that interact with innate immune cells." (PMID 24672527, 2014). "The IL13Rα2pos and mesenchymal tumor lines PBT015, PBT017-4, PBT030 and U251T were shown in our previous work to be lysed by IL13-zetakine+ T cells, and co-injected IL13-zetakine T cells ablate in vivo tumor initiation of these same lines." (PMID 24204956, 2013). "Azoxymethane-induced aberrant crypt focus (ACF; 6 weeks) and tumours (32 weeks) were analysed in wild-type (WT) BALB/c mice, as well as in IL-4Rα−/−, IL-13−/− and ‘double-knockout’ (DKO) animals." (PMID 23784081, 2013). "We used a multistage model of SCC to examine the involvement of elastase (ELA), myeloperoxidase (MPO), nitric oxide (NO), cytokines (IL-6, IL-10, IL-13, IL-17, TGF-β and TNF-α), and neutrophils and macrophages in tumour development." (PMID 23176085, 2012). "The inhibitory activity of IL13, IL1b, PTGS2, NOS2, and CTLA4 on the immune response would enhance tumor growth." (PMID 22013484, 2011). "In contrast, when IL-13Rα2 was knocked-down prior to TSA therapy, the anti-tumor effect of combination of TSA and IL-13-PE was completely eliminated compared to mock vector transfected tumors, which showed dramatic tumor response." (PMID 21477288, 2011). "By day 7, IFNγ, CSF2, CXCL10, GZMB, PTGS2, TNFα, CD80, CCL22, IL12a, IL13, IL1b, IL6, NOS2, and CTLA4 were significantly upregulated in the tumor-bearing mice bladders and AGTR2 and GATA3 were downregulated." (PMID 22013484, 2011). "Terabe and Berzofsky single out IL-13, produced by type II NKT cell in several mouse tumor models, as an important immunosuppressive cytokine, inducing CD11b+Gr-1+ myeloid lineage to secrete TGF-β that finally inhibits CTL induction against the tumor." (PMID 20052413, 2010).
tumor (continued). "Studies using tumor cells have shown that the expression of IL13RA2 up-regulates that of STAT3, which ultimately compromises the IL-13 signal." (PMID 21179488, 2010). "Within the tumour samples, we examined the correlation between SABT1 and the downstream regulated genes: IL-4, IL-13 and MAF-1 using Pearson's correlation coefficient." (PMID 19642980, 2009). "Down-regulation of IL4 Stat, which is an important regulator of signalling from IL13 through the IL4R–STAT6 pathway, is necessary for down-regulation of tumour immuno-surveillance from NKT cells." (PMID 12402156, 2002). "On the contrary, M2-TAMs create an immunosuppressive TME and favor tumor cells for invasion, metastasis, angiogenesis, and remodeling of the ECM by secreting high levels of anti-inflammatory cytokines such as interleukin IL-4, IL-13, and IL-10." (PMID 40805183, 2025). "Furthermore, HMDMs treated with IL-4 + IL-13 separate from those exposed to untreated A375 conditioned media along PC2, in part due to the growth factors present in media from this tumor cell population, such as TGF-alpha and MFG-E8." (PMID 40539073, 2025). "To investigate the role of M2 macrophages in tumor growth, we differentiated THP-1 cells with PMA for 48 h and subsequently induced M2 polarization through additional treatments with human recombinant IL-4 and IL-13 for 48 h." (PMID 40807274, 2025). "Nevertheless, the association between the upregulation of cytokines TGF-β, IL-4/IL-13, IL-10, IL-6, and IL-2 and the overexpression of FAP across multiple tumor types highlights a crucial link between FAP+ CAFs, tumor progression, and evasion of immune surveillance." (PMID 39035007, 2024). "M2 macrophages—“bad macrophages,” induced by Th2 cytokines (e.g., IL-4, IL-10, IL-13), produce anti-inflammatory cytokines (e.g., IL-10, IL-13, TGF-β) promoting tumor growth, ECM remodeling to facilitate tumor invasion, metastasis, angiogenesis, and immune suppression." (PMID 39201585, 2024). "However, in GBM, IL-13Rα2 competitively binds to IL-13, thereby inhibiting the STAT6 signaling pathway, promoting tumor cell invasion, metastasis, and proliferation, and inhibiting tumor cell apoptosis." (PMID 39506843, 2024). "Furthermore, the hyperactivation of miR-155 by STAT5 contributes to a TH2 phenotype, which, through its cytokines (IL-4, IL-5, and IL-13), inhibits the TH1 response, preventing an adequate defense of the organism against the tumor." (PMID 38435536, 2024). "This may result from the underexpression of CCL2 and CCR2, responsible for monocyte recruitment to tumor sites, and the reduced levels of IL4 and IL13, genes known to promote monocyte polarization into M2 macrophages." (PMID 38733987, 2024). "IL-4 and IL-13, which are involved in Th2-type immune responses, are among the major stimuli that induce TAM tendency toward the M2 phenotype that promotes abnormal tumor angiogenesis and tumor progression." (PMID 39403370, 2024). "M2-type macrophages primarily secrete anti-inflammatory cytokines like interleukin 10 (CXCL-10), interleukin 13 (IL-13), and interleukin 4 (IL-4), and express abundant arginine-1, mannose receptor (MR, CD206), and scavenger receptor, which contribute to tumor growth and spread." (PMID 38655133, 2024). "Nevertheless, IL-13 does not act as a growth factor but inhibits IL-2-induced tumor cell proliferation and spontaneous apoptosis of cells in tumor masses." (PMID 39057050, 2024). "With tumor cell stimulation, the CART-19 cells exhibited heightened functional cytokine and chemokine secretion, especially the production of GM-CSF, IFN-γ, IL-2, IL-4, IL-8, IL-12, IL-13, MIP-1α/β, and TNF-α/β." (PMID 38773607, 2024). "In a simple model of cancer cells, IL-13-related pathways can sensitize cells to radiation without consideration of the effects on other types of immune cell but, in tumor-bearing mouse model or humans, this effect is inevitable." (PMID 38264648, 2023).
tumor (continued). "IL‐13 activates the IL‐13 receptor complex to elicit signaling of the JAK1/STAT6 pathway, which may promote cell differentiation and inhibit tumor growth." (PMID 36806727, 2023). "Also, IL-33 exerts tumor supportive action via regulating PPAR-γ-mediated IL-4, IL-13, and IL-15 (Th2 cytokines) release from ILC2s." (PMID 37275901, 2023). "The enhanced production of IL-5 and IL-13 was present in the splenic ILC2s of the tumor-challenged mice regardless of the disappearance of increased numbers of splenic ILC2s over time, which had been observed in tumor-free mice upon the tumor challenge." (PMID 37896962, 2023). "However, Th2 cells are considered to promote tumor progression due to the immunosuppressive substances they release, including TGF-β, IL-4, IL-5, and IL-13." (PMID 38203661, 2023). "IL13-BBζ CAR T cells, however, exhibited clear superiority with regards to tumor killing and CAR T cell persistence and proliferation, with significant numbers of CAR-positive T cells detected in cocultures after tumor cell elimination." (PMID 36968221, 2023). "Using the tumor line A549, which endogenously expresses IL13Rα1, but not IL13Rα2, we found that the IL13-28ζ CAR T cells exhibited the most off-target–mediated degranulation, activation marker expression, in vitro cytotoxicity, and proliferation." (PMID 36968221, 2023). "In addition, it reduced IL-1β, IL-4, IL-6, IL-10, and IL-13 levels, down-regulated PI3K, ERK1/2, and up-regulated EGFR levels, improving the anti-tumor effects of the tumor suppressor microenvironment." (PMID 37397393, 2023). "Tumor-associated macrophages (TAMs) derive from circulating monocytic precursors, infiltrating macrophages in tumor tissue are driven by tumor-derived cytokines (e.g. IL-10, TGF-β) and T cell-derived cytokines (e.g. IL-4, IL-13) and acquire a polarized M2 phenotype." (PMID 37691932, 2023). "IL13-PE also decreased subcutaneous pheochromocytoma, pancreatic, and ACC xenograft tumor burden." (PMID 35464460, 2022). "The expression of Il4, Il13, Ccl11, Ccl17 and Ccl22 mRNA was increased two- to fourfold, whereas the expression of Tslp mRNA was not changed, in the skin lesions of Ddx5∆KC mice compared with Ddx5fl/fl mice at day 16 post-MC903 administration." (PMID 36271146, 2022). "M2 macrophages exert anti-inflammatory effects by secreting anti-inflammatory cytokines, such as IL-4, IL-10, IL-13, and TGF-β, and producing scavenger receptors and other substances; promoting proliferation, invasion and metastasis of tumor cells by inhibiting T-cell activity." (PMID 36131942, 2022). "The TME expression of IL-4/IL-13, absent from the BM, suggests tumor-specific activation of these powerful pathways that drive both immunosuppression and generation of lymphatic vasculature." (PMID 35442077, 2022). "Similarly, the secretion of IL-2, IL-13, and TNF-α is significantly higher in tumour-conditioned media (TCM) derived from 1,4-dihydroxy quininib treated primary UM tumours vs. vehicle." (PMID 36698840, 2022). "Following culture, both splenic and tumor M-MDSCs treated with αIL-4/13Ab-ILC2-SNT had decreased Arg1 expression compared to conAb-ILC2-SNT-treated M-MDSCs, indicating that intestinal ILC2-derived IL-4 and IL-13 can promote Arg1 expression in M-MDSCs." (PMID 35658010, 2022). "Together, these data suggest that IL-4 and IL-13 produced by ILC2s in the tumor niche promote M-MDSC-mediated suppression of anti-tumor immunity and IFNγ production, demonstrating the role of sustained innate signals in shaping the tumor microenvironment." (PMID 35658010, 2022). "In contrast to IL4, there was no change in the number of transmigrated tumor cells after pre-stimulation of BMDMs with IL13 (Met-1 cells, n = 3, p-value = 0.33)." (PMID 36077870, 2022).
tumor (continued). "In the same way, STAT6, also a major signal transducer activated by IL13, can be inhibited by different synthetic molecules (AS1517499, TMC-264, A771726), leading to an inhibition of tumor growth in the 4T1 mammary tumor model and to a modification of genetic markers for TAM infiltration." (PMID 35163420, 2022). "Researchers found that tumor-associated macrophages (TAM) display M2 macrophage characteristics and produce anti-inflammatory cytokines such as interleukin (IL)-10, IL-13 and transforming growth factor-β (TGF-β), promoting tumor initiation, growth, progression, metastasis, and immune evasion 9-12." (PMID 35637970, 2022). "In immune cells, IL-4 and IL-13 can increase polyamine levels that may also contribute to type II NKT cell-mediated tumor immunosuppression." (PMID 36119047, 2022). "Previous studies showed that PD-1 blockade led to the augmentation of effector T cells in tumor sites, increasing the cytolytic activity of tumor-specific cells, increasing production of IL-2, INF-γ, TNF-α, IL-17, and IL-6, and decreasing the production of the Th2 cytokines such as IL-5 and IL-13." (PMID 35996120, 2022). "In addition, IL-13 transmits signals via the IL-13Rα2 and AP-1/ERK pathways to regulate tumor invasion and metastasis." (PMID 35732647, 2022). "Regardless of tumor type, patients with values of sTIM3, IFNα, IFNγ, IL1β, IL1α, IL12p70, MIP1β, IL13, sCD28, sGITR, sPDL1, IL10 and TNFα below the median had longer overall survival (p<0.05)." (PMID 36405727, 2022). "Supporting this hypothesis, the Th2 regulators, Interleukin-4 (IL4) and 13 (IL13), as well as IL10, have been demonstrated to play important roles during primary tumor progression in mouse models of cancer." (PMID 36077870, 2022). "The negative correlations between IL-13 secretion and tumour thickness, and PlGF secretion and chromosome 8 alterations were maintained in both control and 1,4-dihydroxy quininib treated tumours." (PMID 36698840, 2022). "Under conditions of chronic inflammation, IFN-γ secretion by Th1 lymphocytes seems to play a pivotal role in preventing tumor cell proliferation, while IL-13 derived from Th2 lymphocytes and TNF-α, IL-6, and IL-17 produced by Th17 cells promote dysplastic cell proliferation and tumor growth." (PMID 35264972, 2022). "Irrespective of their original functions IL-4 and IL-13 cytokines are capable of promoting tumor cell growth via autocrine and paracrine mechanisms, while inhibiting attacking immune cells at the same time." (PMID 33804263, 2021). "Following differentiation, TH2 cells secrete IL-4, IL-5, IL-10, IL-13, and IL-17, not all of which are beneficial in cancer and have been shown to contribute to the tumor promoting role of this subtype." (PMID 34012451, 2021). "To verify the results of our data analysis, we extracted total RNA from different tumour cell lines (HCT116, SW480, HT29, LOVO, RKO, DLD-1) and the normal epithelial colon cell line NCM460 and measured the mRNA expression levels of TIMP1, PLCG2, BDNF and IL13." (PMID 35003085, 2021). "Altogether, ILC cells including NK cells could contribute to the increased level of TNF-alpha, GM-CSF, IFN-gamma, IL-4, IL-5, IL-13, IL-17, and IL-22, modulating TME and contributing to tumor progression or antitumor activities." (PMID 35008550, 2021). "In tumor biology, macrophages tend to differentiate into the M2 type rather than the tumor-killing M1 phenotype and produce cytokines such as IL-10, IL-4, and IL-13, which can promote tumor progression." (PMID 34148033, 2021). "Considering that IL-13 and IL-4 are primarily derived from lymphocytes, especially Th2 cells, we monitored the Th2 cell population in the lungs of MMTV-PyMT mice and detected increased infiltration of CD4+ T cells and Th2 cells along with tumor progression." (PMID 34707103, 2021). "By using an IL-13 inhibitor (sIL-13Rα2–Fc), they found that IL-13 is essential for the tumor recurrence, while IL-4 is not." (PMID 33450900, 2021).